DHX15 (DEAH-box helicase 15)
Description:
RNA helicase involved in mRNA processing and antiviral innate immunity. Pre-mRNA processing factor involved in disassembly of spliceosomes after the release of mature mRNA. In cooperation with TFIP11 seem to be involved in the transition of the U2, U5 and U6 snRNP-containing IL complex to the snRNP-free IS complex leading to efficient debranching and turnover of excised introns. Plays a key role in antiviral innate immunity by promoting both MAVS-dependent signaling and NLRP6 inflammasome. Acts as an RNA virus sensor: recognizes and binds viral double stranded RNA (dsRNA) and activates the MAVS-dependent signaling to produce interferon-beta and interferon lambda-3 (IFNL3). Involved in intestinal antiviral innate immunity together with NLRP6: recognizes and binds viral dsRNA and promotes activation of the NLRP6 inflammasome in intestinal epithelial cells to restrict infection by enteric viruses. The NLRP6 inflammasome acts by promoting maturation and secretion of IL18 in the extracellular milieu. Also involved in antibacterial innate immunity by promoting Wnt-induced antimicrobial protein expression in Paneth cells (By similarity).
Synonyms: hPrp43; DBP1; DDX15; HRH2; Prp43; PrPp43p; PRPF43
Tractability: Small molecule: a structure with a bound ligand is known. PROTAC: UniProt records ubiquitination sites on it; ubiquitination databases record sites on it; its protein half-life has been measured.
Target class: Enzyme; Hydrolase
Gene: Protein-coding gene on chromosome 4 (24,517,441 to 24,584,603, reverse strand). Ensembl gene ENSG00000109606.
Subcellular location: Nucleus; Nucleus, nucleolus
Subcellular location (Human Protein Atlas): Nuclear speckles
Pathways (Reactome):
Metabolism of RNA: mRNA Polyadenylation; mRNA Splicing - Major Pathway
Chromatin organization: CHD1 and CHD2 subfamily
Disease: Dengue Virus-Host Interactions
Gene Ontology:
Molecular function: ATP hydrolysis activity; double-stranded RNA binding; protein binding; RNA binding; RNA helicase activity; ATP-dependent activity, acting on RNA; helicase activity; ATP binding; nucleic acid binding
Biological process: antiviral innate immune response; defense response to virus; positive regulation of canonical NF-kappaB signal transduction; mRNA processing; mRNA splicing, via spliceosome; RNA splicing; defense response to bacterium; response to alkaloid; response to toxic substance
Cellular component: nuclear speck; nucleus; post-mRNA release spliceosomal complex; spliceosomal complex; U12-type spliceosomal complex; U2-type post-mRNA release spliceosomal complex; nucleoplasm; nucleolus
Genetic constraint (gnomAD): Loss-of-function variants: 7 observed, 84.46 expected, observed/expected ratio (o/e) 0.0829, 90% interval 0.046 to 0.16. The upper end of that interval is the gene's LOEUF score, 0.16, which puts it in group 1 of 6, group 1 being the genes least tolerant of losing a copy. Missense variants: 289 observed, 963.75 expected, observed/expected ratio (o/e) 0.3, 90% interval 0.27 to 0.33. Synonymous variants: 315 observed, 325.78 expected, observed/expected ratio (o/e) 0.97, 90% interval 0.88 to 1.06.
Homologues: Orthologues: chimpanzee DHX15 (100% identical), dog DHX15 (99% identical), macaque DHX15 (99% identical), guinea pig DHX15 (99% identical), pig DHX15 (99% identical), mouse Dhx15 (99% identical), rabbit DHX15 (99% identical), rat Dhx15 (97% identical), tropical clawed frog dhx15 (89% identical), zebrafish dhx15 (89% identical), Drosophila melanogaster Dhx15 (71% identical), Caenorhabditis elegans ddx-15 (68% identical). Paralogues in human: DHX8 (48% identical), DHX16 (44% identical), DHX38 (41% identical), DHX35 (38% identical), DHX33 (35% identical), DHX32 (34% identical), DHX34 (32% identical), DQX1 (32% identical), DHX37 (32% identical), DHX40 (31% identical), DHX29 (30% identical), DHX57 (30% identical), and 6 more.
Diseases named in the same sentence as DHX15 in open-access papers:
DHX15 is named in the same sentence as 47 diseases in open-access papers, as found by Europe PMC text mining. Sharing a sentence is not in itself a finding about the gene and the disease. The quoted sentences say what the papers report.
leukemia (9 papers, 2017 to 2025). A malignant (clonal) hematologic disorder, involving hematopoietic stem cells and characterized by the presence of primitive or atypical myeloid or lymphoid cells in the bone marrow and the blood. "Although previously reported as a tumor suppressor in glioblastoma, DHX15 has also been shown to promote prostate cancer by enhancing androgen receptor transcriptional activity, and its depletion has been linked to leukemia pathogenesis." (PMID 40561176, 2025). "Previous studies showed that DHX15 deficiency leads to DNA damage in human leukemia cells." (PMID 40168451, 2025). "DHX15 knockdown in leukemia cells causes DNA damage and cell cycle arrest." (PMID 40168451, 2025). "Recent studies have suggested that DHX15 mutations can drive leukaemia." (PMID 29512921, 2018). "Several mechanisms have been proposed in these studies to explain the tumorigenicity effect of DHX15, such as the co-activation of the androgen receptor in prostate cancer and the transcriptional activation of NF-kB in leukemia cells." (PMID 34654883, 2021). "DHX15 was down-regulated with leukemia cell apoptosis, and overexpression of DHX15 partially blocked ATO-induced cell apoptosis." (PMID 29163777, 2017). "Silencing DHX15 greatly inhibited leukemia cell proliferation and induced cell apoptosis and G1-phase arrest." (PMID 29163777, 2017). "An expression data set of 1036 tumor cell lines of all types from the Broad Institute database showed increased expression levels of DHX15 in leukemia cell lines compared with other tumor cell lines." (PMID 29163777, 2017). "DHX15 knockdown greatly inhibited cell proliferation, induced cell apoptosis, and led to G1 arrest in leukemia cells." (PMID 29163777, 2017). "DHX15 was down-regulated when AML patients achieved disease remission or when leukemia cell lines were induced to differentiate." (PMID 29163777, 2017). "Knockdown of DHX15 inhibited the nuclear translocation and activation of the NF-kB subunit P65 in leukemia cells." (PMID 29163777, 2017). "DHX15 silencing greatly inhibited leukemia cell proliferation and induced cell apoptosis and G1-phase arrest." (PMID 29163777, 2017). "Mutations in DHX15 and SMC1A correlated with shorter OS in RUNX1/RUNX1T1 leukemia (DHX15: HR = 3.57, p = 0.02; SMC1A: HR = 6.47, p < 0.001), while point mutations in KIT at position D816 correlated with reduced RFS in RUNX1/RUNX1T1 leukemia (HR = 2.27, p = 0.046)." (PMID 31896782, 2020). "Additionally, the correlation between peripheral blood blasts and the DHX15 expression level suggests that the DHX15 expression level possibly predicts the leukaemia burden in the peripheral blood." (PMID 29512921, 2018). "DHX15 plays a role in leukaemogenesis and leukaemia relapse." (PMID 29512921, 2018). "In addition, our experiments also showed higher expression levels of DHX15 in leukemia cell lines, especially in the NB4 and Jurkat cell lines." (PMID 29163777, 2017). "DHX15 was down-regulated when patients who over-expressed DHX15 achieved disease remission, which suggested that DHX15 overexpression occurred mainly in leukemia cells and may be used for minimal residual disease (MRD) detection." (PMID 29163777, 2017). "DHX15 has been implicated in antiviral immune responses through the regulation of the NF-kappaB signaling pathway; we, therefore, explored whether DHX15 participates in leukemia cell proliferation and apoptosis through the NF-kB pathway." (PMID 29163777, 2017). "Therefore, we silenced and restored the expression of DHX15 in the leukemia cell lines NB4 and Jurkat." (PMID 29163777, 2017). "In addition, DHX15 was down-regulated when patients achieved disease remission or when leukemia cell lines were induced to differentiate." (PMID 29163777, 2017). "In addition, we found that DHX15 expression in leukemia cells was significantly decreased in a time-dependent manner with cell differentiation." (PMID 29163777, 2017).
leukemia (continued). "To further explore the clinical significance of these hub genes (SUGP1, DHX16, FUS, HNRNPR, DHX15, NAA38, SKIV2L2, and PLRG1), we used a series of online tools to evaluate the clinical expression of these hub genes in leukemia." (PMID 31766457, 2019). "This is the first study to investigate the role of DHX15, a member of the DEAH-box RNA helicase family, in the pathogenesis and progression of leukemia." (PMID 29163777, 2017). "In our data, nanosecond pulsed electric field exposure provoked significant increases of DHX15 and DHX16 expression in Jurkat cells, indicating that nanosecond pulsed electric fields treatment may affect the gene expression of leukemia cells." (PMID 31766457, 2019). "In contrast, DHX15 was commonly over-expressed in AML patients and leukemia cell lines." (PMID 29163777, 2017).
virus infection (9 papers, 2018 to 2025). "DHX15 has also been implicated in the immune response to viral infection." (PMID 30397098, 2018). "DHX15 is found primarily in the nucleus, although it localizes to the cytoplasm during virus infection." (PMID 40168451, 2025). "We next assessed the effect of Dhx15 knockdown on gene expression in the context of virus infection." (PMID 36441781, 2022). "First, DHX15 participates in innate immune response against viral infection by regulating several signaling pathways." (PMID 35193582, 2022). "Our findings suggest that DHX15 may have evolved to limit the potential damage that APOBEC3 proteins can inflict on the genome when they are induced during virus infection." (PMID 40168451, 2025). "However, there is considerable evidence that human DHX15 acts as a PRR for dsRNA in response to virus infection." (PMID 37509194, 2023). "Furthermore, depletion of Dhx15 increases susceptibility of human cells to infection with a variety of distinct RNA viruses, indicating that, similar to our findings, Dhx15 regulates antiviral signaling in the context of a broad range of virus infections." (PMID 36441781, 2022). "Interestingly, in vertebrates, the orthologues of Dhx15 have previously been proposed to regulate transcriptional responses to virus infection by modulating signal transduction of core immune pathways such as MAPK (mitogen-activated protein kinase), NFκB, and RIG-I like receptor (RLR) signaling." (PMID 36441781, 2022). "However, another study showed that loss of DHX15 has no impact on inflammasome activation during virus infection, suggesting a DHX15-independent manner of NLRP6 inflammasome activation." (PMID 36825215, 2022). "Rig-I, MDA5, and members of DExD/H-box RNA helicases including DHX15 that recognize dsRNA and these receptors signal via MAVS which isa critical downstream adaptor in RLR signaling that drives the innate response to virus infection." (PMID 39772220, 2024). "Several studies reported that DHX15 activates p38 MAPK and NF-κB signaling pathway during anti-virus infection." (PMID 35193582, 2022). "Moreover, it was found that the RNA helicase DEAH-box helicase 15 (DHX15) activates the NLRP6 inflammasome and IL-18 production during viral infection in mouse IECs." (PMID 39611173, 2024). "Given the important roles of AECs and respiratory viral infection in asthma development and exacerbation, TRIM29 and DHX15 modulators may mitigate asthma by influencing AEC pyroptosis and immune response during viral infection." (PMID 39611173, 2024). "The majority of these (194 out of 229 upregulated genes and 89 out of 143 downregulated genes) overlapped with the differentially expressed genes in uninfected samples, defining a set of genes with robust Dhx15-dependent differential expression, regardless of virus infection." (PMID 36441781, 2022). "aegypti ortholog of mammalian DHX15, a DEAH-box helicase, is antiviral against CHIKV, although this appears to be dependent on its function in regulating glycolysis as opposed to sensing virus infection directly." (PMID 37509194, 2023).
COVID-19 (6 papers, 2021 to 2025). A disease caused by infection with severe acute respiratory syndrome coronavirus 2. "A gene variant of NUDCD1 influences COVID-19 severity in Asians through interacting with DHX15 and MAVS, affecting effective response against SARS-CoV-2." (PMID 40534864, 2025). "Furthermore, DHX15 is essential in the context of mild/severe COVID-19 and its association with hepatocellular carcinoma and chronic hepatitis B." (PMID 38699234, 2024). "Four upregulated common genes (DHX15, USP14, COPS3, TYK2) and one downregulated common feature gene (RIOK2) were identified and showed good diagnostic accuracy for T2DM and COVID-19." (PMID 38699234, 2024). "We constructed a PPI network and identified five common feature genes (DHX15, USP14, COPS3, TYK2, and RIOK) of T2DM and COVID-19 by extracting the core genes of the network." (PMID 38699234, 2024). "We identified five common feature genes between T2DM and COVID-19: DHX15, USP14, COPS3, TYK2, and RIOK2 (where DHX15, USP14, COPS3, and TYK2 were upregulated and RIOK2 was downregulated)." (PMID 38699234, 2024). "The roles of DHX15, USP14, COPS3, TYK2, and RIOK2 in T2DM and COVID-19 remain primarily unknown, emphasizing the importance of future research." (PMID 38699234, 2024). "We identified five common feature genes (DHX15, USP14, COPS3, TYK2, and RIOK2) and their co-regulatory pathways between T2DM and COVID-19, which may provide new insights for further molecular mechanism studies." (PMID 38699234, 2024). "The results from the ROC curve analysis showed that DHX15, USP14, COPS3, TYK2, and RIOK had AUC values of 0.931, 0.917, 0.986, 0.903, and 0.917, respectively, for T2DM and AUC values of 0.960, 0.860, 1.0, 0.9, and 0.90, respectively, for COVID-19." (PMID 38699234, 2024). "We identified five common feature genes (DHX15, USP14, COPS3, TYK2, and RIOK2) and their co-regulatory pathways between T2DM and COVID-19, which may provide new insights for molecular mechanism studies." (PMID 38699234, 2024). "In the validation dataset, the AUC values of DHX15, USP14, COPS3, TYK2, and RIOK were 0.922, 0.781, 0.812, 0.844, and 0.984, respectively, for T2DM, and 0.733, 0.687, 0.737, 0.782, and 0.632, respectively, for COVID-19." (PMID 38699234, 2024).
breast carcinoma (5 papers, 2018 to 2025). "DHX15 can interact with circRNF10 to isolate DHX15 from p65 and inhibit the progression of breast cancer by inhibiting the nuclear factor kappa-light-chain-enhancer of activated B cells (NF-κB) pathway." (PMID 41461671, 2025). "DHX15 has been reported to form a positive feedback loop with the oncogenic transcription factor NF-κB p65, thus promoting breast cancer progression." (PMID 40541951, 2025). "DHX15 contributes as a cancer promoter in breast cancer, prostate cancer, acute myeloid leukemia, and hepatocellular carcinoma, and as an antitumor factor in glioma due to its growth inhibitory function." (PMID 38612527, 2024). "DHX15 acts as a cancer promoter in breast cancer, prostate cancer, acute myeloid leukemia, and hepatocellular carcinoma (HCC), and as an antitumor factor in glioma due to its growth inhibitory function." (PMID 38612527, 2024).
hepatocellular carcinoma (5 papers, 2020 to 2025). A malignant tumor that arises from hepatocytes. "Recently, DHX15 has been shown to be associated with clinically pathological elements and prognosis in patients with hepatocellular carcinoma (HCC)." (PMID 33644083, 2020). "Increased DHX15 expression has also been correlated with a poor prognosis in hepatocellular carcinoma patients." (PMID 40541951, 2025). "Recently, two different studies evaluated DHX15 expression in hepatocellular carcinoma patients, showing a differential expression of this helicase." (PMID 38612527, 2024). "We further found that mTORC1 is involved in DHX15-mediated regulation of autophagy and that DHX15 inhibits proliferation of hepatocellular carcinoma (HCC) cells by suppressing autophagy." (PMID 33644083, 2020). "More importantly, we found that depletion of DHX15 increased hepatoma cell proliferation in a manner dependent on the DHX15-mediated regulation of autophagy." (PMID 33644083, 2020). "Regarding the potential use of DHX15 as a diagnostic marker for liver disease, patients with hepatocellular carcinoma showed increased levels of DHX15 in blood samples compared with subjects without hepatic affectation." (PMID 38612527, 2024). "In addition, Dhx15 gene silencing significantly hindered primary tumor growth in the hepatocellular carcinoma experimental model." (PMID 38612527, 2024). "In conclusion, Dhx15 is a key regulator of liver physiology and organogenesis, is increased in the blood of cirrhotic and hepatocellular carcinoma patients, and plays a key role in controlling hepatocellular carcinoma tumor growth and expansion in experimental models." (PMID 38612527, 2024). "In addition, several studies have demonstrated the overexpression of DHX15 in the context of hepatocellular carcinoma." (PMID 38612527, 2024). "Furthermore, we found that DHX15 acts as a suppressor of proliferation in hepatoma cells and that this function is dependent on autophagy inhibition." (PMID 33644083, 2020). "Next, we evaluated the role of Dhx15 in the context of hepatocellular carcinoma (HCC) and liver metastasis." (PMID 38612527, 2024). "In hepatocellular carcinoma (HCC), DHX15 was found to be overexpressed in human cancerous livers." (PMID 38612527, 2024). "Previously, many studies have found that DHX9, DHX15, DDX24, DHX29, etc. are widely involved in tumor progression through various pathways, however, the role of DHX37, as an important member of the DEAD/H-box RNA helicase family, in hepatocellular carcinoma progression has been less studied." (PMID 37958405, 2023).
prostate carcinoma (5 papers, 2018 to 2025). A carcinoma that arises from epithelial cells of the prostate gland. "Studies have reported that DHX15 contributes to carcinogenesis in several malignancies including prostate cancer, non-small cell lung cancer, and hepatocellular carcinoma." (PMID 38402201, 2024).
acute myeloid leukemia (3 papers, 2017 to 2024). Acute myeloid leukemia (AML) is a group of neoplasms arising from precursor cells committed to the myeloid cell-line differentiation. "Our previous study found that the DHX15 gene was overexpressed in acute lymphoblastic leukemia (ALL) and acute myeloid leukemia (AML) patients." (PMID 35193582, 2022).
glioma (3 papers, 2020 to 2025). A benign or malignant brain and spinal cord tumor that arises from glial cells (astrocytes, oligodendrocytes, ependymal cells). "In glioma, DHX15 is an antitumour gene, and its Ia–Ib and III–IV motifs, but not its ATPase activity, play important roles in its growth-inhibitory function." (PMID 33644083, 2020). "DHX15, though reported to act as a tumor suppressor in some cancers, may contribute to glioma progression via androgen receptor signaling and warrants further study." (PMID 40561176, 2025). "Moreover, DHX15 not only dysregulates genes downstream of the NF-kB signaling pathway, an important mechanism of its antitumour function, but also downregulates genes involved in splicing and ribosomal biogenesis in glioma, indicating that DHX15 regulates glioma at the post-transcriptional level." (PMID 33644083, 2020).
diabetes (2 papers, 2024 to 2025). "DHX15 may contribute to the progression of diabetes by affecting pancreatic beta cells." (PMID 38699234, 2024).
lung carcinoma (2 papers, 2024). "Since we previously found lymphatic alterations and reduced metastasis in a lung cancer mouse model in Dhx15 heterozygous mice, we now evaluated the role of Dhx15 in HCC and liver metastasis in mice." (PMID 38612527, 2024). "Furthermore, CCNB1 and CCNA2 were vital in regulating cell cycle progression, while BRCA1 was involved in DNA repair, damage, and chromatin remodeling and DHX15 overexpression has been shown to promote proliferation and tumor metastasis, particularly in lung cancers." (PMID 38233752, 2024).